KRAS (KRas proto-oncogene, GTPase)
Diseases named in the same sentence as KRAS in open-access papers (continued):
Sharing a sentence is not in itself a finding about the gene and the disease.
lung cancer (continued). "HK2 knockout can inhibit tumorigenesis in mouse models of KRAS-driven lung cancer, ErbB2-driven breast cancer, and PTEN-deficient PC." (PMID 39770959, 2024). "KRAS is known to be a key player in progression of many cancers including lung cancer, either owing to several missense mutations or due to its overexpression." (PMID 39201772, 2024). "Understanding the interplay between Ferredoxin 1 and metabolic pathways in KRAS mutant lung cancer provides valuable insights into the underlying mechanisms driving tumorigenesis and identifies potential targets for therapeutic intervention." (PMID 38802900, 2024). "Case in point, the most common RAS mutations in lung cancer are G12C/V/D in KRAS, but Q61R/K in NRAS in melanoma." (PMID 38547169, 2024). "The most common oncogenic driver mutations for non–small cell lung cancer (NSCLC) activate EGFR or KRAS." (PMID 38639476, 2024). "Herein, we explored the association between HOXC10 expression and KRAS-mutant lung cancer bone metastasis." (PMID 39191757, 2024). "The inhibition of ERK5 is a potential complementary strategy for countering FAK inhibitor resistance in patients with lung cancer harboring KRAS mutations." (PMID 39271958, 2024). "In lung cancer targeting, the KRAS G12C mutation has been shown to have add-on effects/synergy with other treatments such as mTOR and IGF1R inhibitors in vitro and in vivo." (PMID 38607041, 2024). "In lung cancer (non-small cell lung cancer), the common KRAS mutation is the KRAS G12C (glycine mutated into cysteine) and, importantly, two inhibitors have been developed: sotorasib and adagrasib, both of which FDA approved." (PMID 38607041, 2024). "Review of the cBioPortal datasets gave us further insight to conduct an overall survival comparison between low and high mRNA expression levels of cytosolic NADPH generating enzymes in lung cancer patients with KRAS wild type (WT) and KRAS mutation." (PMID 38997257, 2024). "PARP4 depletion or mutation (I1039T) promotes the tumorigenicity of KRAS- or EGFR-driven lung cancer cells." (PMID 39034402, 2024). "Despite the high incidence of KRAS mutations in pancreatic, colorectal, and lung cancers, there are still few effective treatments for KRAS-driven cancers." (PMID 38275900, 2024). "By doing so, we aim to provide a comprehensive understanding of the landscape of missense mutations in KRAS and their potential implications in lung cancer." (PMID 38374309, 2024). "KRAS mutations combined with deletion of the LKB1 tumor suppressor gene (KL) are strongly linked to aggressive forms of lung cancer." (PMID 39192357, 2024). "Another study suggested that there was a direct association between SPP1 and KRAS mutation in lung cancer and that SPP1 deficiency had a protective effect on patients with KRAS mutation in lung cancer." (PMID 38919629, 2024). "KRAS gene mutations are one of the main causes of lung adenocarcinoma, and the activation of KRAS in lung cancer can enhance the activity of SREBP through the ERK-mTORC1 pathway, thereby stimulating the synthesis of fatty acids." (PMID 39744129, 2024). "KRAS mutations are common in many types of cancer, including lung cancer, colon cancer, and pancreatic cancer." (PMID 39453005, 2024). "Several biomarkers (such as EGFR, BRAF, KRAS gene mutations, etc.)have emerged as predictive and prognostic markers for lung cancer." (PMID 38730722, 2024). "The co-occurrence of EGFR and KRAS mutations negatively affects lung cancer development by inducing oncogenic stress and leading to synthetic lethality." (PMID 38938274, 2024).
lung cancer (continued). "Notable examples include the presence of mutated KRAS, which has been associated with an unfavorable prognosis in pancreatic and lung cancer, as well as the presence of mutated NRAS, which has been related to a poor prognosis in metastatic melanoma." (PMID 38399367, 2024). "KRAS, a critical oncogenic driver of lung cancer, is frequently co-mutated in lung cancers: 27% of patients with KRAS mutations also have deleterious mutations in KEAP1/NFE2L2 genes, comprised of 24% KEAP1 and 3% NFE2L2 co-mutations." (PMID 38542481, 2024). "Although the function of IBP2 in cancers is not clear, high expression of IBP2 has been associated with PTEN mutations in glioblastoma, breast, and prostate cancers and KRAS mutations in lung cancer." (PMID 38172678, 2024). "Substantial documents show that KRAS activation mutations widely existed in sundry malignant carcinoma including pancreatic, colon cancers and lung cancers, and closely involved with undesirable progression and prognosis in clinic cancer therapy." (PMID 38872211, 2024). "sorted out the types and proportion of KRAS mutations according to different types and races of lung cancer first, and then the biological and co-mutations of KRAS in lung cancer were described, as well as the influence on prognosis." (PMID 38706597, 2024). "The frequency of KRAS mutations in cases of MPE were lower than in patients with lung cancer at 19% versus 33%, respectively." (PMID 39596989, 2024). "This study provides valuable outcome information from a real-world cohort of Latin America patients with NSCLC harboring KRAS mutations and emphasizes the prognostic impact of diverse molecular profiles in this genomically-defined subset of lung cancer." (PMID 37490263, 2024). "KRAS p.G12C hot spot mutations has rapidly modified diagnostic algorithm for lung cancer patients electing Non-Small Cell Lung Cancer (NSCLC) patients to target treatment." (PMID 40026570, 2024). "This emphasizes that oncogenic events play a crucial role in determining the dependence and associated mechanisms of distinct subtypes of KRAS-driven lung cancer on G6PD." (PMID 38997257, 2024). "In recent years, significant advancements in treating lung cancer subtypes with KRAS G12C mutations have led to an increase in patient survival." (PMID 39763604, 2024). "KRAS oncogenic mutations are very frequent in lung cancer and the leading causes of cancer-related deaths worldwide." (PMID 39322643, 2024). "KRAS-mutated lung cancers are frequently distinguished by a significant quantity of T cell infiltrates that enhance neutrophil recruitment, leading to immune exclusion and T cell suppression." (PMID 39802954, 2024). "KEAP1 mutations confer worse outcomes to immunotherapy among lung cancer patients with KRAS mutation, and KEAP1 mutations results in distinct immunophenotypes in KRAS mution of lung cancer." (PMID 38884095, 2024). "It is noteworthy that A549 lung cancer cells harbor the KRAS G12S mutation, while H1299 cells lack KRAS mutations." (PMID 39518013, 2024). "After 40 years of research, patients with KRAS G12C-mutated lung cancer can now benefit from novel KRAS-targeting drugs." (PMID 39594840, 2024). "The advent of novel inhibitors against KRAS mutations will further improve survival of lung cancer patients." (PMID 38846975, 2024). "LKB1 inactivation in KRAS mutant lung cancer cells causes cytoplasmic accumulation of mitochondrial DNA due to defects in autophagy and mitochondrial dysfunction, which triggers activation of STING signaling." (PMID 39544365, 2024). "In the present work, we found that trametinib mediated MEK1/2 inhibition downregulates Id1 protein levels in human and murine lung cancer cells, regardless KRAS-mutational status." (PMID 38643157, 2024). "Mechanistic studies in lung cancer indicate that the hippo pathway is implicated in KRAS G12C resistance, highlighting its therapeutic potential in augmenting KRAS inhibitors." (PMID 39199569, 2024).
lung cancer (continued). "Our study uncovers a previously undefined mechanism of ferroptosis resistance involving LDH isoenzymes and provides a novel rationale for exploiting oncogene-specific ferroptosis susceptibility to treat KRAS-driven lung cancer." (PMID 39643712, 2024). "Multiple studies converge in finding pancreatic, colorectal and lung cancer most commonly express KRAS mutations." (PMID 39372214, 2024). "Among other factors, higher DNA adduct levels and more frequent mutations in the proto-oncogene KRAS in females have also been cited as a possible contributor governing higher lung cancer risk in females." (PMID 39107837, 2024). "STK11/LKB1 mutations are the main cause of primary resistance to PD-1 inhibitors in KRAS-mutant lung cancer." (PMID 39252322, 2024). "A recent in vivo study has shown that when WT-HRAS and WT-NRAS interact with mutated KRAS, specifically G12D in lung cancer, it effectively reduces KRAS dimerization, as well as decreases the amount of ERK downstream signaling." (PMID 39184150, 2024). "This case presents educational CT images of P-ADC and suggests the importance of considering pan-ERBB inhibitors in clinical trials for the treatment of KRAS-mutated lung cancer." (PMID 38659041, 2024). "As PARP4 copy number loss was associated with EGFR and KRAS mutations, we selected two additional classic lung cancer cell lines bearing EGFR or KRAS mutations that had moderate basal PARP4 expression." (PMID 39034402, 2024). "In lung cancer, the detrimental activity of the oncogenic KRAS-G12D variant into the responsiveness to ICIs has been largely demonstrated." (PMID 38280995, 2024). "The mutation of G12C is one of the diagnostic markers among KRAS mutations of lung cancer patients with tobacco exposure." (PMID 39056802, 2024). "Mutated KRAS is the most common driver gene in lung adenocarcinoma, the most common histological subtype of lung cancer, in White and Black Americans alike." (PMID 39436906, 2024). "In some studies, lung cancers with KRAS mutations have been associated with inferior overall survival (OS) compared to KRAS wild-type tumors, especially in the advanced stages, although the evidence is still inconclusive." (PMID 38785486, 2024). "We propose ERK5 inhibition as a potential co-targeting strategy to counteract FAK inhibitor resistance in lung cancer patients with KRAS mutations." (PMID 39271958, 2024). "While KRAS mutation is the leading cause of low survival rates in lung cancer bone metastasis patients, effective treatments are still lacking." (PMID 39191757, 2024). "Recently, novel specific KRAS c.34G>T (p.G12C) protein inhibitors have shown promising results for better survival in non‐small cell lung cancer patients with KRAS c.34G>T (p.G12C)‐mutated tumors." (PMID 39039804, 2024). "Further, KRAS is mutated in pancreatic and lung cancer, NRAS in melanoma and HRAS in oral and skin SCC." (PMID 38963974, 2024). "Aberrant constitutive KRAS signaling drives cell proliferation, and several types of cancer, including pancreatic, colorectal, and lung cancer, exhibit KRAS-activating mutations with high incidence." (PMID 38979184, 2024). "KRAS-mutant lung carcinomas with LKB1 and/or KEAP1 co-mutations have intrinsic therapeutic resistance." (PMID 38949950, 2024). "In particular, it has been shown that tumor suppressors have differential ability to promote oncogenesis in the context of KRAS mutated lung cancer with distinct therapeutic vulnerabilities." (PMID 37470475, 2023). "At the same time, we investigated the effect of the compounds on the growth inhibition of A549 and H460 lung cancer cells bearing KRAS and LKB1 mutations." (PMID 37242466, 2023). "In lung cancers, the prognostic significance of KRAS mutations has been the source of much debate, with some studies suggesting a shorter OS in KRAS mutant lung cancers but others suggesting the contrary." (PMID 38067288, 2023).
lung cancer (continued). "LKB1 loss commonly co-occurs with therapeutically intractable KRAS mutations in lung cancer (KL tumors) and defines an oncogenotype with particularly aggressive features and poor outcomes." (PMID 37035141, 2023). "Mutations in the RAS genes are among the most mutated genes associated with cancer (mutated in 90% of pancreatic, 35% of lung and 45% of colon cancers) and in particular KRAS, is the isoform prevalently mutated in lung cancers." (PMID 37251335, 2023). "KRAS mutation positive lung cancer is known to be clinically characterized by older age, males, and smokers." (PMID 37751775, 2023). "The prognostic and predictive implications of KRAS mutations have been analyzed across various stages of lung cancer in multiple meta-analyses." (PMID 37373999, 2023). "Dysregulation of receptor tyrosine kinase (RTK) signaling leads to lung cancer, such as activating EGFR mutations are present in 15% of NSCLC, BRAF and KRAS always also mutated in lung cancer." (PMID 37061730, 2023). "We analyzed the transcriptomes of 3D human lung cancer spheroids that harbor KRAS(G12C) mutations to determine the landscape of TE RNAs regulated by mutant KRAS(G12C)." (PMID 36909578, 2023). "In all lung cancers, KRAS mutations mainly accounted for 11.2–25.3% of all mutations, with the KRAS G12C-type mutations accounting for 2.8–15%." (PMID 36675641, 2023). "For example, mutations in KRAS proto-oncogene and GTPase(KRAS) exist in most tumours, such as lung cancer, colon cancer, and pancreatic cancer, and introduce mutated KRAS (KRASG12D) into normal human breast cells, which can initiate breast cancer." (PMID 37108242, 2023). "Let-7 overexpression in lung cancer cells harboring KRAS mutation induces both cell cycle arrest and cell death, leading to suppression of tumor growth both in vitro and in vivo." (PMID 37511536, 2023). "A previous study showed a relationship between KRAS mutations and mucinous differentiation in cancers of various human organs, including colorectal and lung cancer." (PMID 37751775, 2023). "Data from preclinical studies presented at the AACR in 2022 showed that the drug LY-3537982 had good activity, with inhibiting KRAS-GTP binding in lung cancer cell lines carrying the KARSG12C variant." (PMID 37669923, 2023). "The combination of AZ628 and BP-1-102 significantly suppressed MEK/ERK signaling pathway activation in lung cancer cells harboring KRAS mutations." (PMID 38111008, 2023). "Another critical question—which upstream kinases regulate IKKα activation—warrants further investigation because EGFR and KRAS are highly mutated in lung cancer patients." (PMID 36966223, 2023). "Mutation of KRAS was first initiated in lung cancer in the 1980s, which is a gene that is hard to target." (PMID 37065830, 2023). "In lung cancer patients with tumors harboring a KRAS mutation, high UHRF1 expression is anticorrelated with tumor suppressor gene expression and predicts poor patient survival." (PMID 37407562, 2023). "Small molecule inhibitors have been developed to specifically target KRAS mutations and have been tested in solid tumour models including colorectal, pancreatic, ovarian, and lung cancer." (PMID 36723696, 2023). "In 3 independent cohorts of patients with lung cancer, the KRAS mutation status positively correlated with CD47 expression." (PMID 36413402, 2023). "Here, we discovered that HIF1A-As2, a KRAS-responsive lncRNA, is upregulated in lung cancer and its high expression is associated with a poor patient prognosis." (PMID 37041291, 2023).
lung cancer (continued). "KRAS mutations have been considered a key driver of lung cancer, in which KRAS p.G12C accounts for 45% to 50% of KRAS mutations." (PMID 38269023, 2023). "As new treatment options for patients with KRAS-mutated lung cancers become available, the need for improved methods of testing for KRAS mutations becomes more important." (PMID 38067288, 2023). "For instance, KRAS-G12V mutations are associated with worse outcomes than KRAS-G12D mutations in patients with lung cancer." (PMID 37662925, 2023). "They all regulate the expression of lung cancer-associated genes KRAS, c-Myc, SOCS1, SATB2, PTEN, PDCD4, Bcl-2, TGFBR2, ZEB1, Cyclin D1, ZEB2, RECK, EGFL7, and KLF4." (PMID 37631277, 2023). "Gene detection results of lung cancer tissue biopsy showed that the KRAS gene G12D was mutated and PD-L1 was positive, with a tumor proportion score of 95% (Dako 22C3 IHC platform)." (PMID 36800626, 2023). "In a previous study, KV showed an anticancer effect in KRAS-mutated lung cancer via the PI3K-AKT-mTOR and RAF-ERK signaling pathways." (PMID 37174108, 2023). "On the contrary, CCL5, of which expression was elevated by KRAS mutated lung cancer, exhibited antitumor abilities by recruiting T cells to the TME." (PMID 38097680, 2023). "KRAS mutations are found in approximately 35% of all lung adenocarcinomas, making it a paramount driver of this particular lung cancer subtype." (PMID 37580790, 2023). "DNA methylation, in turn, has been associated with the presence of KRAS mutations in colorectal and lung cancer." (PMID 36383274, 2023). "KRAS mutant lung cancer has three variants: type-1 is a characterized by mucinous histology with TTF1 expression, type-2 is characterized by high TMB and PDL1 expression while type-3 group contains KEAP mutation." (PMID 38239281, 2023). "It is widely accepted that KRAS mutation in lung cancer is smoking associated but it is only proven for G12C while the G12D and G12V are associated with chromosomal instability and/or mismatch repair deficiency." (PMID 38239281, 2023). "While not always directly translatable to CRC, the progress in targeting KRAS-mutated lung cancer can still inform on potential strategies to test in CRC." (PMID 37569406, 2023). "In this study, we utilized a variety of cell models that harbored common driver mutations in lung cancer including KRAS substitution (A549) and EGFR activation mutations (HCC827, H1975)." (PMID 36709476, 2023). "KV is a pure compound from a plant extract that exhibits anticancer/antitumor effects by inactivating AKT signaling and inhibiting the RAF-ERK signaling pathway in KRAS-mutated lung cancer cells." (PMID 37174108, 2023). "Previous studies have also demonstrated excellent predictive performance of data analysis and machine learning for KRAS mutations in colon and lung cancers." (PMID 38268915, 2023).